SV2B (synaptic vesicle glycoprotein 2B)
Description:
Probably plays a role in the control of regulated secretion in neural and endocrine cells. (Microbial infection) Receptor for the C.botulinum neurotoxin type A2 (BoNT/A, botA); glycosylation is not essential but enhances the interaction. Probably also serves as a receptor for the closely related C.botulinum neurotoxin type A1.
Synonyms: KIAA0735; HsT19680; SLC22B2
Tractability: Small molecule: a drug acting on it is in phase 2 or 3 trials; a structure with a bound ligand is known; it belongs to a druggable protein family. Antibody: its Gene Ontology location is reachable by antibodies, with high confidence; UniProt predicts a signal peptide or a membrane-spanning region. PROTAC: its protein half-life has been measured.
Gene: Protein-coding gene on chromosome 15 (91,099,869 to 91,302,565, forward strand). Ensembl gene ENSG00000185518.
Subcellular location: Cytoplasmic vesicle, secretory vesicle, synaptic vesicle membrane; Cytoplasmic vesicle, secretory vesicle, acrosome
Pathways (Reactome):
Disease: Toxicity of botulinum toxin type A (botA); Toxicity of botulinum toxin type D (botD); Toxicity of botulinum toxin type E (botE); Toxicity of botulinum toxin type F (botF)
Gene Ontology:
Molecular function: protein binding; transmembrane transporter activity
Biological process: regulation of presynaptic cytosolic calcium ion concentration; regulation of synaptic vesicle exocytosis; chemical synaptic transmission; transmembrane transport
Cellular component: membrane; plasma membrane; synaptic vesicle; synaptic vesicle membrane; acrosomal vesicle
Genetic constraint (gnomAD): Loss-of-function variants: 39 observed, 74.91 expected, observed/expected ratio (o/e) 0.52, 90% interval 0.4 to 0.68. The upper end of that interval is the gene's LOEUF score, 0.68, which puts it in group 2 of 6, group 1 being the genes least tolerant of losing a copy. Missense variants: 758 observed, 899.25 expected, observed/expected ratio (o/e) 0.84, 90% interval 0.79 to 0.89. Synonymous variants: 312 observed, 329.53 expected, observed/expected ratio (o/e) 0.95, 90% interval 0.86 to 1.04.
Homologues: Orthologues: chimpanzee SV2B (99% identical), guinea pig SV2B (96% identical), dog SV2B (96% identical), rat Sv2b (95% identical), mouse Sv2b (95% identical), pig SV2B (94% identical), macaque SV2B (93% identical), rabbit SV2B (84% identical), tropical clawed frog sv2b (76% identical), zebrafish sv2bb (64% identical), zebrafish sv2ba (60% identical). Paralogues in human: SV2A (64% identical), SV2C (61% identical).
Diseases named in the same sentence as SV2B in open-access papers:
SV2B is named in the same sentence as 39 diseases in open-access papers, as found by Europe PMC text mining. Sharing a sentence is not in itself a finding about the gene and the disease. The quoted sentences say what the papers report.
epilepsy (7 papers, 2013 to 2026). A brain disorder characterized by episodes of abnormally increased neuronal discharge resulting in transient episodes of sensory or motor neurological dysfunction, or psychic dysfunction. "The proteins SV2A and SV2B regulate presynaptic Ca2+ accumulation, action potential-dependent neurotransmitter release in e.g., hippocampal neurons and their absence induces epilepsy e.g., SV2A deficiency showed elevated seizure vulnerability in an SV2A knockout model of zebrafish." (PMID 36406753, 2022). "The isoforms SV2A, SV2B and SV2C are implicated in neurological diseases such as epilepsy, Alzheimer's and Parkinson's disease." (PMID 33588752, 2021). "SV2B has been shown to regulate presynaptic Ca2+ signaling and has also been suggested as a target for treatment of epilepsy." (PMID 23550224, 2013).
Alzheimer disease (4 papers, 2020 to 2025). A progressive, neurodegenerative disease characterized by loss of function and death of nerve cells in several areas of the brain leading to loss of cognitive function such as memory and language. "Several recent studies have implicated a range of genes, including Sv2b, Park2, Sept5, and Atxn2, in the development of neurological disorders, cognitive impairment, and neurodegenerative diseases such as Alzheimer’s disease (AD) and Parkinson’s disease (PD)." (PMID 40943361, 2025). "Several other diseases, such as missense mutations in leukemia, Alzheimer's disease, retinal neuropathy and kidney disease, have been known to be closely associated with SV2B, suggesting that the protein is involved in many aspects of human disease." (PMID 32667033, 2020). "These compounds have been shown to upregulate the expression of Rab3a and SV2B proteins, restoring electrophysiological function in human embryonic stem cell-derived Alzheimer’s disease models." (PMID 40659647, 2025).
glioblastoma (4 papers, 2020 to 2026). The most malignant astrocytic tumor (WHO grade IV). "SV2B was identified as a key prognosis-associated marker in glioblastoma multiforme and prostate cancer." (PMID 33178362, 2020). "Based on current findings, we are proposing that the SV2B/miR-34a/miR-128 axis could serve as a putative prognostic biomarker for glioblastoma multiforme." (PMID 38503772, 2024). "Furthermore, the expression levels SV2B suggested that it can act as a prognostic marker, enhancing its clinical relevance in combating yet incurable highly malignant brain tumours, such as glioblastoma and medulloblastoma." (PMID 38503772, 2024). "The analysis depicted significant differences of SV2B levels between astrocytomas, IDH-wildtype diffuse astrocytic tumours, and oligodendrogliomas when compared to glioblastomas, the latter expressing higher protein abundance within patient samples." (PMID 38503772, 2024).
glioma (4 papers, 2020 to 2025). A benign or malignant brain and spinal cord tumor that arises from glial cells (astrocytes, oligodendrocytes, ependymal cells). "Previous bioinformatics studies suggested that SV2B expression may be associated with glioma grade or unfavourable prognosis, suggesting its oncogenic properties." (PMID 38503772, 2024). "SV2B was found upregulated in high grade glioma tissues and exerted potential as a clinical prognostic marker." (PMID 38503772, 2024). "Given SV2B’s role in synaptically active regions and its involvement in glioma progression, its expression and function might have implications in paediatric MB." (PMID 40596133, 2025). "SV2B was found to be differentially expressed in glioma grade II." (PMID 35571016, 2022). "Only a few members of the SV2 protein family, such as SV2B and SV2C, have been found to be differentially expressed in glioma grade II." (PMID 32667033, 2020). "Despite the heightened activity in gliomas, it is important to acknowledge that their activity may not be solely dependent on SV2B." (PMID 38503772, 2024). "Although gliomas are active, their activity may not be exclusive to SV2B." (PMID 32667033, 2020).
Parkinson disease (3 papers, 2017 to 2025). A progressive degenerative disorder of the central nervous system characterized by loss of dopamine producing neurons in the substantia nigra and the presence of Lewy bodies in the substantia nigra and locus coeruleus. "Some of the genes that were steadily down-regulated, such as Pink1, Park 2, Sv2b, Gabbr2, Sept5 and Atxn2, were directly related to Parkinson’s onset." (PMID 29156651, 2017).
virus infection (3 papers, 2024 to 2025). "TBC1D24 and SV2B were not enriched in previous genome-scalescreens that reproducibly identified host dependency factors for direct flavivirusinfection (37, –, 41) andhave no known roles in virus infection in general." (PMID 39377586, 2024). "TBC1D24 and SV2B were not enriched in previous genome-scale screens that reproducibly identified host dependency factors for direct flavivirus infection and have no known roles in virus infection in general." (PMID 38712102, 2024).
brain tumours (2 papers, 2024 to 2025). "Malignant brain tumours evidently expressed higher levels of SV2B when compared to normal and normal adjacent tissue samples, reaching significance." (PMID 38503772, 2024). "Significant differences of measured SV2B levels were seen between grades 1 and 2 in comparison to grade 4 brain tumour samples." (PMID 38503772, 2024). "The effect of current miRNA regulation on SV2B protein function was validated using brain tumour patient samples, including GBM." (PMID 38503772, 2024). "The elevated expression levels of CORO1C and SV2B suggested that they could serve as putative prognostic biomarkers, enhancing their clinical relevance in combating highly malignant brain tumours like MB and GB." (PMID 40596133, 2025). "Thus, it could be suggested that SV2B could potentially act as an oncogene hence its high abundance in highly malignant brain tumours." (PMID 38503772, 2024).
dengue disease (2 papers, 2024). Dengue fever (DF), caused by dengue virus, is an arboviral disease characterized by an initial non-specific febrile illness that can sometimes progress to more severe forms manifesting capillary leakage and hemorrhage (dengue hemorrhagic fever, or DHF) and shock (dengue shock syndrome, or DSS). "Further validation and mechanistic studies of TBC1D24, SV2B, and other screen hits can also lay the foundation for discovering host proteins and pathways that can be targeted by antiviral drugs to thwart dengue disease." (PMID 38712102, 2024).
gastric cancer (2 papers, 2020 to 2022). A primary or metastatic malignant neoplasm involving the stomach. "According to the discussion above, we considered that SV2B and SDC2 deserved to be further studied in gastric cancer." (PMID 33178362, 2020). "As for SV2B and SDC2, encoding a member of the synaptic vesicle protein 2 and syndecan 2, respectively, both of them have not been fully studied in gastric cancer." (PMID 33178362, 2020).
prostate carcinoma (2 papers, 2020). A carcinoma that arises from epithelial cells of the prostate gland. "For instance, in prostate cancer, miR-106a-5p has been found to modulate SV2B expression, and regulate vesicle translocation and cytosis." (PMID 32667033, 2020).
astrocytomas (1 paper, 2024). "Medulloblastomas also possessed a significantly higher abundance of SV2B in comparison to astrocytomas." (PMID 38503772, 2024).
lung adenocarcinoma (1 paper, 2024). A carcinoma that arises from the lung and is characterized by the presence of malignant glandular epithelial cells. "In conclusion, this is the first report of a novel SV2B-ALK and EML4-ALK double-fusion in a lung adenocarcinoma patient with extensive metastases." (PMID 39735595, 2024).
medulloblastoma (1 paper, 2024). A malignant, invasive embryonal neoplasm arising from the cerebellum. "This is in support with our IHC results, which depicted significantly high SV2B protein expression in high grade brain malignancies, such as medulloblastoma and GBM, respectively." (PMID 38503772, 2024).
metastatic disease (1 paper, 2024). "In conclusion, the presented work identified the seven genes EMILIN3, MTA1, SV2B, TMPRSS6, ACVR1C, NFAT5 and SMC3 associated with the formation of colorectal BM during the course of disease but not with liver metastasis or non-metastatic disease." (PMID 38558282, 2024).
Obesity (1 paper, 2021). Accumulation of substantial excess body fat. "Among the presynaptic vesicle proteins analyzed, i.e., synaptic vesicle glycoproteins 2A and 2C (SVA and SVC, respectively), only synaptic vesicle glycoprotein 2B (SV2B) showed alterations related to obesity and age." (PMID 34685507, 2021).
prostate small cell carcinoma (1 paper, 2019). A neuroendocrine carcinoma of the prostate gland with unfavorable prognosis, composed of small cells containing neurosecretory granules. "In contrast, the SV2B isoform is related with prostate small cell carcinoma and the SV2C isoform is generally associated with the correct functioning of basal ganglia nuclei." (PMID 31052478, 2019).
tumor (7 papers, 2020 to 2026). "Furthermore, SV2B has been shown to be associated with energy metabolism, since the exuberant material energy requirements within the tumor can highly rely on SV2B in the regulation of transporter protein activity, glucose transport and other functions." (PMID 32667033, 2020). "Additionally, SV2B has been demonstrated to be associated with energy metabolism, as the substantial energy requirements within the tumour may heavily depend on SV2B for regulating transporter protein activity, glucose transport, and other functions." (PMID 38503772, 2024). "In all datasets, the primary source of variation (PC1) was likely associated with tumour purity as demonstrated by the expression of neuronal genes, with neuron marker genes like SLC12A5, TMEM130 and SV2B ranking among the top 50 contributors." (PMID 39382765, 2024). "Grades 3 and 4 were shown to express much higher levels of SV2B in comparison to lower tumour grades." (PMID 38503772, 2024). "Two studies have identified the potential role of SV2B in promoting tumor metastasis, with MMP9, COL3A1 and SV2B being identified as important hub genes that are associated with ECM–receptor interaction." (PMID 32667033, 2020). "We uncovered a new role for the SV2B protein in promoting tumor growth." (PMID 41199339, 2026). "In addition, SV2B expression was substantially higher than that of SV2A and SV2C in TFE3‐RCC tissues, suggesting that padsevonil inhibited tumor progression in TFE3‐RCC primarily by targeting SV2B." (PMID 41199339, 2026). "In GB, tumour cells form glutamatergic synapses with neurons, and SV2B may support this pathological communication by facilitating synaptic vesicle fusion and excitatory signalling that drives tumour growth." (PMID 40596133, 2025). "Our IHC findings revealed that the expression of SV2B increased with tumour grade, which suggested that highly metabolically active malignancies might require more of the protein to be able to proliferate and metastasise." (PMID 38503772, 2024). "The role of SV2B in regulating the activity of transporter and transmembrane transporter proteins, which then introduces glucose-induced particles into the plasma membrane, has been shown to be essential in providing nutrients for tumor cells." (PMID 32667033, 2020). "High SV2B expression was significantly associated with poorer overall survival in both tumour types, supporting its role as a potential negative prognostic marker and suggesting a contribution to tumour aggressiveness." (PMID 40596133, 2025). "Therefore, it can be inferred that SV2B may also, to a lesser extent, play a role in promoting tumor progression by promoting the migration of tumor cells." (PMID 32667033, 2020). "The significant under expression of SV2B within NAT could be a result of the particular characteristics within this type of tissue that makes it a separate entity and distinguishes it from both healthy and tumour tissue." (PMID 38503772, 2024).
infection (5 papers, 2010 to 2024). The state of being infected such as from the introduction of a foreign agent such as serum, vaccine, antigenic substance or organism. "FcgRIIa-KO, TBC1D24-KO, and SV2B-KO K562-DCSIGN clones reduced the efficiency of direct infection to relatively similar levels compared to the unedited (WT) K562-DCSIGN cell pool, (median reduction of 33%, 27%, 24%, respectively)." (PMID 38712102, 2024). "The effect of TBC1D24 or SV2B KO on ADE efficiency wasnot overcome even under a high multiplicity of infection conditions used in ourscreens." (PMID 39377586, 2024). "Specifically, the strongest ADE reduction was observed for DENV3, andthe weakest for DENV2 (~80% and ~30% reduction in peak infection, respectively).SV2B KO reduced peak enhancement of infection of both DENV1 and DENV4 by~50%." (PMID 39377586, 2024). "An alternative explanation is that in addition to its requirement for efficient ADE, SV2B may play a minor role in direct infection." (PMID 38712102, 2024). "Next, to confirm that the roles of TBC1D24 and SV2B are unique to IgG-mediated infection, we generated corresponding clonal KO lines in K562 cells engineered to express DCSIGN (K562-DCSIGN), a cellular attachment factor that permits direct DENV infection in the absence of IgG antibodies." (PMID 38712102, 2024). "Although the median reduction in direct infection efficiency of SV2B KO clones was comparable to control FcgRIIa KO clones, we note that two of four SV2B KO clones displayed a substantial reduction in direct infection efficiency compared to WT K562-DCSIGN cells." (PMID 38712102, 2024). "SV2B KO reduced peak enhancement of infection of both DENV1 and DENV4 by ~50%." (PMID 38712102, 2024). "Furtherstudies using additional clones will be required to clarify the relativecontribution of SV2B and TBC1D24 to ADE and direct infection." (PMID 39377586, 2024). "Further studies using additional clones will be required to clarify the relative contribution of SV2B to ADE and direct infection." (PMID 38712102, 2024). "Inaddition to their role in promoting efficient ADE, SV2B, and TBC1D24 may play aminor role in direct infection." (PMID 39377586, 2024). "One limitation of our study is that although we validated the requirement of TBC1D24 and SV2B for efficient ADE in multiple cell lines, we were unable to confirm our findings in primary cells due to difficulty in maintaining cell viability following CRISPR editing and subsequent infection via ADE." (PMID 38712102, 2024). "In addition, we cultured SV2B and SV2A/B KO spinal cord neurons and observed that while SV2B KO mice were still sensitive to the addition of TeNT, SV2A/B double KO spinal neurons were protected from TeNT; again the neurons were re-sensitized to the toxin after infection with SV2A virus." (PMID 21124874, 2010). "It is possible that infection with DENV via ADE upregulates the otherwise limited endogenous expression of TBC1D24 and SV2B proteins in non-neuronal cells." (PMID 38712102, 2024).
gastrointestinal tumors (1 paper, 2020). "SV2B has been demonstrated to be overexpressed in many digestive tract tumors, especially in pancreatic and gastrointestinal tumors." (PMID 32667033, 2020).
neurodegenerative disease (1 paper, 2025). A disorder of the central nervous system characterized by gradual and progressive loss of neural tissue and neurologic function. "Emerging research has highlighted the involvement of specific genes, including Sv2b, Park2, Sept5, Atxn2, Pink1, and Gabbr2, in neurological dysfunction and neurodegenerative diseases." (PMID 40943361, 2025).
neurodevelopmental disorder (1 paper, 2021). A behavioral and cognitive disorder with onset during the developmental period that involves impaired or aberrant development of intellectual, motor, or social functions. "Whereas there is currently no study on the synaptic vesicle glycoprotein 2B in insects, neurobeachin was associated in D. melanogaster to neurodevelopmental disorders, disruption of synaptic properties and impaired behavior or associative learning." (PMID 33670203, 2021).
psychiatric disorder (1 paper, 2017). A disorder characterized by behavioral and/or psychological abnormalities, often accompanied by physical symptoms. "Besides GRID1, top markers mapped to within or near NPAS3, which potentially regulates genes involved in neurogenesis and has been previously associated with psychiatric disorders; and SV2B, a synaptic vesicle protein-encoding gene implicated in cognitive processes in model systems." (PMID 28360924, 2017).
SV2B also shares sentences with these, for which no sentence is quoted: cancer (4 papers); Cognitive impairment (2); neurological diseases (2); oligodendroglioma (2); bipolar disorder (1); brain cancer (1); breast carcinoma (1); colitis (1); Flavivirus Infections (1); gout (1); kidney disease (1); leukemia (1); migraine (1); neuroblastoma (1); Parkinson’s (1); partial epilepsy (1); renal cell carcinoma (1).